OSGEP (O-sialoglycoprotein endopeptidase)
Description:
Component of the EKC/KEOPS complex that is required for the formation of a threonylcarbamoyl group on adenosine at position 37 (t(6)A37) in tRNAs that read codons beginning with adenine. The complex is probably involved in the transfer of the threonylcarbamoyl moiety of threonylcarbamoyl-AMP (TC-AMP) to the N6 group of A37. OSGEP likely plays a direct catalytic role in this reaction, but requires other protein(s) of the complex to fulfill this activity.
Synonyms: GCPL1; PRSMG1; OSGEP1; KAE1; TCS3; GAMOS3
Tractability: PROTAC: ubiquitination databases record sites on it; its protein half-life has been measured.
Target class: Enzyme; Transferase
Gene: Protein-coding gene on chromosome 14 (20,446,401 to 20,455,089, reverse strand). Ensembl gene ENSG00000092094.
Subcellular location: Cytoplasm; Nucleus
Subcellular location (Human Protein Atlas): Nucleoplasm; Cytosol
Pathways (Reactome):
Metabolism of RNA: tRNA modification in the nucleus and cytosol
Gene Ontology:
Molecular function: protein binding; tRNA N(6)-L-threonylcarbamoyladenine synthase activity; acyltransferase activity, transferring groups other than amino-acyl groups
Biological process: tRNA modification; tRNA threonylcarbamoyladenosine modification; maintenance of translational fidelity
Cellular component: cytoplasm; cytosol; EKC/KEOPS complex; nucleoplasm; nucleus
Genetic constraint (gnomAD): Loss-of-function variants: 31 observed, 37.25 expected, observed/expected ratio (o/e) 0.83, 90% interval 0.62 to 1.12. The upper end of that interval is the gene's LOEUF score, 1.12, which puts it in group 4 of 6, group 1 being the genes least tolerant of losing a copy. Missense variants: 381 observed, 441.4 expected, observed/expected ratio (o/e) 0.86, 90% interval 0.79 to 0.94. Synonymous variants: 132 observed, 162.45 expected, observed/expected ratio (o/e) 0.81, 90% interval 0.7 to 0.94.
Homologues: Orthologues: chimpanzee OSGEP (100% identical), macaque OSGEP (99% identical), pig OSGEP (98% identical), guinea pig OSGEP (96% identical), dog OSGEP (96% identical), rabbit OSGEP (96% identical), rat Osgep (95% identical), mouse Osgep (93% identical), zebrafish osgep (84% identical), tropical clawed frog osgep (76% identical), Drosophila melanogaster Tcs3 (72% identical), Caenorhabditis elegans Y71H2AM.1 (69% identical). Paralogues in human: OSGEPL1 (28% identical).
Diseases named in the same sentence as OSGEP in open-access papers:
OSGEP is named in the same sentence as 25 diseases in open-access papers, as found by Europe PMC text mining. Sharing a sentence is not in itself a finding about the gene and the disease. The quoted sentences say what the papers report.
Galloway-Mowat syndrome (8 papers, 2018 to 2025). Galloway syndrome is characterized by the association of nephrotic syndrome and central nervous system anomalies. "For example, mutations in OSGEP, TP53RK, TPRKB, LAGE3 and C14orf142, encoding all five subunits of the human cytoplasmic KEOPS complex, lead to defective t6A modification and Galloway-Mowat syndrome (GAMOS), characterised by early-onset nephrotic syndrome, microcephaly and brain anomalies." (PMID 32047918, 2020). "Loss-of-function mutations in OSGEP, TP53RK, TPRKN or LAGE3, which encode the four subunits of the KEOPS complex (Kinase, Endopeptidase and Other Protein of small Size) result in Galloway-Mowat syndrome (GAMOS, #MIM251300), an early-onset nephrotic disorder with severe PM." (PMID 31832602, 2019). "The term “Galloway-Mowat syndrome 1 (GAMOS1)” is now used for GAMOS caused by mutations in WDR73, and “Galloway-Mowat syndrome 2-5 (GAMOS2-5)” is used for GAMOS with mutations in LAGE3, OSGEP, TP53RK, and TPRKB, respectively." (PMID 30558655, 2018). "We recently identified autosomal recessive mutations in genes encoding four of the five subunits of human KEOPS complex, namely LAGE3, OSGEP, TP53RK, and TPRKB in patients with Galloway-Mowat syndrome (GAMOS, OMIM#251300)." (PMID 31481669, 2019). "Galloway-Mowat syndrome (GAMOS) is a group of rare hereditary diseases by the combination of early onset steroid-resistant nephrotic syndrome (SRNS) and microcephaly with brain anomalies caused by WDR73, LAGE3, OSGEP, TP53RK, TPRKB, GON7, WDR4 or NUP133 mutations." (PMID 36755238, 2023).
microcephaly (7 papers, 2018 to 2025). A congenital or acquired developmental disorder in which the circumference of the head is smaller than normal for the person's age and sex. "Moreover, acute OSGEP knockout in zebrafish larvae had a significantly reduced survival rate and a smaller microcephaly index." (PMID 38456959, 2025).
nephrotic syndrome (7 papers, 2016 to 2025). A collection of symptoms that include severe edema, proteinuria, and hypoalbuminemia; it is indicative of renal dysfunction. "These two cases, in conjunction with the findings of a literature review, indicate that OSGEP pathogenic variants are associated with an earlier onset of nephrotic syndrome and shorter life expectancy than WDR73 pathogenic variants." (PMID 30975089, 2019). "It has been reported that OSGEP and TP53RK, both of which are implicated in nephrotic syndrome with primary microcephaly, interact with components of the ARP2/3 complex including ARPC1B involved in actin remodeling at lamellipodia." (PMID 29333229, 2016). "An in vivo study recently showed that knockdown of OSGEP and TP53RK resulted in defects in the actin cytoskeleton and a decrease of human podocyte migration rate; these findings are compatible with the pathological manifestation in the development of nephrotic syndrome." (PMID 30558655, 2018).
Arachnodactyly (1 paper, 2018). "Arachnodactyly or camptodactyly was noted in all of our patients (caused by an OSGEP mutation) and has been frequently observed in Taiwanese patients affected with GAMOS." (PMID 30558655, 2018).
Cerebellar atrophy (1 paper, 2018). Cerebellar atrophy is defined as a cerebellum with initially normal structures, in a posterior fossa with normal size, which displays enlarged fissures (interfolial spaces) in comparison to the foliae secondary to loss of tissue. "Cerebellar atrophy was also found in 9 out of 28 patients with OSGEP mutations, including our patient III-2." (PMID 30558655, 2018).
ischemia (1 paper, 2025). A hypoperfusion of the BLOOD through an organ or tissue caused by a PATHOLOGIC CONSTRICTION or obstruction of its BLOOD VESSELS, or an absence of BLOOD CIRCULATION. "Consistent with in vitro data, OSGEP expression level gradually decreased following different time periods of ischemia and reperfusion, and the minimum appeared at 90 min in ischemic period and 6 h after reperfusion." (PMID 38456959, 2025).
melanoma (1 paper, 2026). A malignant, usually aggressive tumor composed of atypical, neoplastic melanocytes. "We discovered that OSGEP loss triggers melanoma regression by relocating RIG-I to stress granules, leading to its pathway activation." (PMID 41735308, 2026).
Pleural effusion (1 paper, 2020). The presence of an excessive amount of fluid in the pleural cavity. "One patient with homozygous OSGEP mutations died before 4 months of age due to severe pleural effusions." (PMID 33333793, 2020).
tumor (3 papers, 2021 to 2026). "Here, we reveal how O-sialoglycoprotein endopeptidase (OSGEP), catalysing the tRNA modification N6-threonylcarbamoyladenosine (t6A), drives protein homeostasis in cancer cells to maintain T-cell exclusion and prevent anti-tumour immune response." (PMID 41735308, 2026).
cancer (2 papers, 2024 to 2026). A tumor composed of atypical neoplastic, often pleomorphic cells that invade other tissues. "While the downregulated gene OSGEP is associated with tRNA modification, and its mutations can lead to various neurological abnormalities, SMKR1 is involved in the process of cancer occurrence, which is closely related to cancer recurrence." (PMID 38891594, 2024).
kidney disease (1 paper, 2019). "Variant analyses of patients 1 and 2 were performed by targeted massive parallel sequencing using an updated version of our kidney disease gene panel that includes more than 200 genes causative of or associated with inherited kidney diseases (including WDR73, TPRKB, TP53RK, LARGE3, and OSGEP genes)." (PMID 30975089, 2019).
neurodevelopmental disorder (1 paper, 2024). A behavioral and cognitive disorder with onset during the developmental period that involves impaired or aberrant development of intellectual, motor, or social functions. "Further research is warranted to unravel the intricate mechanisms underlying the interplay between OSGEP, proteostasis, and autophagy in the context of neurodevelopmental disorders." (PMID 39063131, 2024).
OSGEP also shares sentences with these, for which no sentence is quoted: distal renal tubular acidosis (6 papers); Primary microcephaly (4); focal segmental glomerulosclerosis (2); autosomal recessive disease (1); brain disorder (1); Camptodactyly (1); Diffuse mesangial sclerosis (1); fungal meningitis (1); hepatocellular carcinoma (1); Hypertension (1); minimal change disease (1); papillary thyroid carcinoma (1); Sjögren syndrome (1).